HMGB1 (high mobility group box 1)
Diseases named in the same sentence as HMGB1 in open-access papers (continued):
Sharing a sentence is not in itself a finding about the gene and the disease.
injury (continued). "Because DAMPs are released from cells undergoing necroptosis, we measured the levels of circulating levels of high‐mobility group box‐1 (HMGB1) protein, a DAMP that has been shown to be released by hepatic necroptosis and is associated with acute liver injury and chronic liver disease." (PMID 34761505, 2021). "Anti-HMGB1 polyclonal antibody significantly attenuates serum elevations of alanine aminotransferase and abrogates markers of inflammation and improves survival in a model of acetaminophen-acute liver injury." (PMID 33925132, 2021). "LPS-induced acute lung injury was also ameliorated by sodium butyrate with reduced HMGB1 release." (PMID 33456673, 2020). "In addition, cytoplasmic HMGB1 has been reported to be expressed by neurons after traumatic brain injury." (PMID 33036632, 2020). "Based on these findings, we speculate that differences in previously reported HMGB1 concentrations in comparable populations of trauma patients might be caused by variability in pre-analytical conditions." (PMID 31892315, 2019). "In addition, a recent study reported that blockade of HMGB1 using anti-HMGB1 antibody reduces acute brain edema after traumatic brain injury through inhibition of inflammatory responses." (PMID 29699567, 2018). "Previous research showed that LPS could induce HMGB1 production in BEAS-2B cells and trigger acute lung injury, and that it stimulated HMGB1 secretion in RAW264.7 cells." (PMID 29702580, 2018). "Targeting interactions between TLRs or RAGE and their shared ligand (HMGB1) may be a clinically relevant strategy to prevent or treat kidney injury but also confirm the mechanism by which TLRs and RAGE are activated in DN." (PMID 29844451, 2018). "The underlying mechanisms of hepatic IRI still remain unclear, of which some mediators have been found playing indispensable roles in liver IRI induced lung injury, including high mobility group box-1 protein (HMGB1), adrenaline and N-acetyl-cysteine." (PMID 30522479, 2018). "Given that metformin directly inhibited HMGB1 cytokine activity as demonstrated in this study, the target of metformin in this acetaminophen-induced liver injury could be endogenous HMGB1 that was released from damaged hepatocytes." (PMID 28373282, 2017). "Understanding the protective mechanism of enoxaparin related with the reduction of HMGB1 may help further knowledge of the effects of mechanical forces in the lung and development of possible therapeutic strategies involved in acute lung injury." (PMID 21726460, 2011). "Finally, patients who later developed organ injury, (acute lung injury and acute renal failure) had also significantly higher plasma levels of HMGB1 early after trauma." (PMID 19887013, 2009). "Notably, numerous studies have suggested that targeting the HMGB1/NF‐κB signaling pathway could be potential therapeutic strategy for treating HI‐induced brain injury in neonates." (PMID 39496476, 2024). "Moreover, paeonol increased the expression of HMGB1 in the nucleus, inhibited the production of HMGB1 in the cytoplasm and decreased the expression of P65 both in the nucleus and cytoplasm of lung tissue cells in LPS-induced acute lung injury rats." (PMID 36501418, 2022). "Therefore, targeting pathways that block the accumulation of extracellular HMGB1 by GTS-21 may provide a novel approach for developing therapies to treat oxidative stress-induced inflammatory lung injury in patients on oxygen therapy." (PMID 32600307, 2020). "In addition, the transcriptional regulator High mobility group box protein 1 (HMGB1), normally located in the cytosol, is released during necrosis and contributes to inflammation e.g., in acute lung injury, and one of the main exocytic routes of HMGB1 is via exosomes." (PMID 28491866, 2017). "Considering that HMGB1 can induce NS/PC proliferation, and is secreted by reactive astrocytes following brain injury, it is highly possible that HMGB1 released by astrocytes may potentiate NS/PC proliferation following brain injury." (PMID 24970310, 2014).
injury (continued). "On the other hand, the roles of histones in immune responses are poorly understood in comparison with HMGB1, whereas our previous studies strongly suggested the significance of Ab response against histone H1 for overcoming rejection and for the protection of Con A-induced acute liver injury." (PMID 24454474, 2013). "Therefore, mediators in addition to HMGB1 could be crucial role in initiating and maintaining astrocyte activitation following nerve injury." (PMID 23991202, 2013). "The levels of SBDP145, melatonin, sLOX-1, HMGB1 and HIF-1α were highly expressed in preterm newborns with brain injury, and the levels were higher when the condition of the newborns was more severe." (PMID 39256844, 2024). "Western blotting revealed that paeonol also inhibited the total expression of HMGB1, NF-κB P65 and TNF-α in the lung tissue of acute lung injury rats." (PMID 36501418, 2022). "HMGB1/TLR4 signaling promotes neutrophil migration and contributes to paraquat-induced acute lung injury." (PMID 33925132, 2021). "High-mobility group box-1 (HMGB1) protein, a member of the high-mobility group 1 (HMG-1) family, modulates cell death in acute liver injury by NF-κB signal pathway activated by advanced glycan end products (RAGE) and toll-like receptor 4 (TLR4)." (PMID 34366845, 2021). "HMGB1 has also been shown to drive the alveolar macrophage production of inflammatory factors, including IL-1β and TNF-α, thereby inducing acute lung injury." (PMID 31958320, 2020). "Our findings, along with these data, suggest that HMGB1 is the missing link between complement activation and liver injury in the APAP-induced liver injury mouse model." (PMID 29696019, 2018). "In demonstrating the reduction in inflammation by XBJ, we investigated potential molecular mechanisms mediating the effect, such as HMGB1 and RAGE, which recently have been proved to act as an important part to the development of acute lung injury." (PMID 25821501, 2015). "The serum concentrations of SBDP145, melatonin, sLOX-1, HMGB1 and HIF-1α in newborns with different severity of ventricular hemorrhage were observed, and the levels of SBDP145, melatonin, sLOX-1, HMGB1 and HIF-1α in those with different severity of white matter brain injury were compared." (PMID 39256844, 2024). "In an APAP-induced acute liver injury model, the metabolic product of APAP, N-acetyl-p-benzoquinoneimine, induces mitochondrial dysfunction and eventual cell necrosis, as well as the release of DAMP molecules like HMGB1 and heat-shock proteins." (PMID 29696019, 2018). "The ISS is correlated with adrenaline, interleukin (IL)-6, histone-complexed DNA fragments, high-mobility group box 1 (HMGB1), soluble thrombomodulin (sTM) and protein C in trauma patients with high serum SDC-1 levels (≥ 63 ng/ml) but not in those with low SDC-1 levels (< 63 ng/ml)." (PMID 36237551, 2022). "It is interesting to note here that a similar modulation of NOD2 signaling by extracellular HMGB1, not cytosolic HMGB1, has been reported in an animal model of acute lung injury, wherein extracellular HMGB1/TLR4 signaling activates NOD2, which induces autophagy and suppresses NOD2-RIP2 signaling." (PMID 35954253, 2022). "In addition, the administration of anti-HMGB1 neutralizing antibodies has been shown to preserve BBB integrity and suppress the expression of inflammatory molecules such as TNF-α in the case of brain injury." (PMID 23874584, 2013). "The levels of SBDP145, melatonin, sLOX-1, HMGB1, and HIF-1α in newborns with preterm brain injury were not dynamically analyzed, and further investigation into the dynamic changes of these markers is warranted." (PMID 39256844, 2024).
ischemic stroke (88 papers, 2010 to 2025). A stroke disorder caused by obstruction of blood flow to the brain, due to thrombotic (local blood clot formation) or embolic (due to a blood clot or other material traveling from another site) event. "Taken together, the underlying mechanisms in the immune function of HMGB1 on Treg after ischemic stroke remains to be elucidated." (PMID 38740617, 2025). "HMGB1 has been strongly implicated in triggering neuroinflammatory responses that lead to neuronal injury and cognitive decline after ischemic stroke through multiple signaling mechanisms." (PMID 38708343, 2024). "High‐mobility group box 1 protein (HMGB1) is extensively involved in causing ischemic stroke, pathological damage of ischemic brain injury, and neural tissue repair after ischemic brain injury." (PMID 37062906, 2023). "To overcome limitations associated with anti-HMGB1 treatments, we focused on targeting NETs to improve ischemic stroke outcomes." (PMID 35358095, 2022). "Following ischemic stroke, damaged neurons release damage associated molecular patterns (DAMPs), such as high mobility group box 1 (HMGB1)." (PMID 36588708, 2022). "Ischemic stroke is a disease caused by cerebral arterial stenosis that releases high-mobility group box 1 (HMGB1) to the extracellular spaces and results in inflammatory reactions." (PMID 39698442, 2022). "HMGB1 has been shown to be translocated in the cytosol after ischemic stroke and is released extracellularly, which is implicated in the blood–brain barrier (BBB) impairment, neuroimmune activation, and neuronal demise." (PMID 36232519, 2022). "HMGB1, a damage-associated protein, mediates neuroinflammation and brain damage in many neurological diseases including ischemic stroke." (PMID 31920543, 2019). "Acting as an endogenous danger-associated molecular pattern (DAMP) protein, HMGB1 mediates cerebral inflammation and brain injury and participates in the pathogenesis of ischemic stroke." (PMID 31001089, 2019). "In ischemic stroke, which is associated with minimal bleeding, HMGB1 released from necrotic cells triggers inflammatory responses and leads to secondary brain damage." (PMID 28646881, 2017). "HMGB1 is also a critical mediator of both the primary and secondary damage caused by ischemic strokes." (PMID 27544687, 2016). "Oil acetic acid significantly reduces plaque HMGB1, can attenuate carotid plaque instability, and may potentially reduce the risk of ischemic stroke." (PMID 38740617, 2025). "In addition, there is a strong correlation between MMP-9 and HMGB1 levels in ischemic stroke patients, which was associated with poor outcome." (PMID 31291966, 2019). "After the onset of ischemic stroke, microglial activation can occur from minutes to a few hours after ischemic stroke and is driven by damage-associated molecular patterns (including high mobility group box 1, toll-like receptors and peroxiredoxins) from cell debris or apoptotic neuron cells." (PMID 37464832, 2023). "HMGB1 participates in blood–brain barrier disruption and inflammatory response, and its potential as a therapeutic target for mitigating post-ischemic stroke complications such as hemorrhagic transformation after thrombolysis or infection needs to be explored." (PMID 38740617, 2025). "The study of the immune mechanisms of HMGB1 in ischemic stroke provides new insights into neuroprotective therapy." (PMID 38740617, 2025). "HMGB1-mediated inflammation is closely related to the development of ischemic stroke and hemorrhagic transformation, including glial cell activation, peripheral inflammatory cell infiltration, and release of inflammatory factors." (PMID 38740617, 2025). "Another factor from the DAMP group, which can be released passively by necrotic cells or actively by activated immune cells, is HMGB1 with its dual role after ischemic stroke." (PMID 40332314, 2025). "Antithrombotic drugs using HMGB1 as a target in the prevention and treatment of ischemic stroke need to be further investigated." (PMID 38740617, 2025).
ischemic stroke (continued). "The effects of different redox forms of HMGB1 on the complex roles of neuroimmunity and functional recovery in ischemic stroke at different times need further investigation." (PMID 38740617, 2025). "A study by Tsukagawa demonstrated that serum and plasma HMGB1 levels were significantly elevated in patients with ischemic stroke." (PMID 40066310, 2025). "Given its multifaceted role, HMGB1 is recognized as a crucial therapeutic target and prognostic marker for ischemic stroke and hemorrhagic transformation." (PMID 38740617, 2025). "High mobility group box 1 (HMGB1) has been identified as a potential diagnostic and prognostic biomarker for ischemic stroke." (PMID 40066310, 2025). "In this review, we elucidate the structural and redox properties, release mechanisms, receptors, and complex roles of HMGB1 in ischemic stroke, focusing on the part of HMGB1 with related neuroglia and immune cells and in hemorrhagic transformation." (PMID 38740617, 2025). "HMGB1 expression increases after ischemic stroke and further affects the expression of TLR4, RAGE and other related inflammatory factors, thus reducing the inflammatory response and ultimately protecting against injury." (PMID 40128654, 2025). "An increase in HMGB1 expression leads to the aggravation of inflammatory reactions after ischemic stroke." (PMID 40128654, 2025). "As a proinflammatory molecule, HMGB1 can play a role in the development and progression of ischemic stroke." (PMID 40128654, 2025). "It has been shown that HMGB1 is detected in all thrombus emboli and co-localizes with neutrophils and NETs, participating in NETs-mediated thrombosis and ischemic stroke development." (PMID 38740617, 2025). "Further elucidation is needed regarding the mechanism of HMGB1-induced autophagosome formation on thrombus formation in ischemic stroke." (PMID 38740617, 2025). "In this prospective cohort investigation, heightened concentrations of HMGB1 in the serum during the acute phase following ischemic stroke emerged as an independent predictor of cognitive dysfunction assessed at the 3-month follow-up time point." (PMID 38708343, 2024). "For example, in the classic TLR2/4 mice, after ischemic stroke, TLR2/4 binds to the endogenous ligand HMGB1, activating a series of signal transduction cascades, which then produce pro-inflammatory cytokines affecting the prognosis of ischemic stroke." (PMID 39649720, 2024). "During ischemic stroke, neurons release HMGB1, a key DAMP that exacerbates inflammation and promotes apoptosis." (PMID 39598404, 2024). "The role of HMGB1 in ischemic stroke has been extensively documented, with its release contributing to neuroinflammation and blood-brain barrier disruption—processes that glycyrrhizin effectively mitigates." (PMID 39598404, 2024). "HMGB1 potently induces hepcidin not only in the brain but also in the liver, thereby influencing systemic iron homeostasis following ischemic stroke." (PMID 39349828, 2024). "HMGB1 also plays a role in neurovascular repair by influencing the paracrine functions of endothelial progenitor cells (EPCs) after ischemic stroke." (PMID 39598404, 2024). "Cortical astrocytes located in the penumbra of an ischemic stroke rat model show enhanced levels of high mobility group box 1 (HMGB1) and its receptor TLR4." (PMID 38674050, 2024). "GA’s ability to inhibit HMGB1 protein, a key mediator of inflammation, underscores its potential in treating ischemic stroke." (PMID 39598404, 2024). "In short, our results suggest a critical role for PMPs derived HMGB1 in the formation of detrimental NETs in the acute phase of ischemic stroke." (PMID 38233928, 2024). "In a recent study, a long-acting tissue Klk has been shown to reduce HMGB1 release by neurons and microglial cells after ischemic stroke." (PMID 39337564, 2024).
ischemic stroke (continued). "In conclusion, these findings open promising new avenues of research to confirm HMGB1 as a clinically viable biomarker and to elucidate its role in cognitive prognosis after ischemic stroke." (PMID 38708343, 2024). "Secondly, more research is needed to elucidate the mechanisms by which heightened HMGB1 contributes to secondary neurodegeneration and cognitive impairment after ischemic stroke." (PMID 38708343, 2024). "The key discovery that heightened HMGB1 concentrations in the acute phase following ischemic stroke correlate with an amplified probability of developing PSCI is consistent with and expands upon the findings reported by multiple prior investigations." (PMID 38708343, 2024). "To study the interaction HMGB1 drived from PMVs and the formation of NETs in ischemic stroke model, we depleted microvesicles with lactadherin." (PMID 38233928, 2024). "This study aimed to address critical gaps in knowledge by evaluating serum HMGB1 levels drawn within 24 h of ischemic stroke as a predictor of cognitive impairment determined by validated neuropsychological screening at 3-month follow-up." (PMID 38708343, 2024). "In a recent study, HMGB1 from platelets mediated NETosis contribute to brain injury in ischemic stroke." (PMID 38233928, 2024). "High-mobility group box-1 (HMGB1) is released from neuronal nuclei after acute damage, such as ischemic stroke." (PMID 37834242, 2023). "The potential modulation of cGAS sensitivity to dsDNA by HMGB1 presents a novel perspective for pharmacological intervention in ischemic stroke through HMGB1 antagonists or monoclonal antibodies." (PMID 37915571, 2023). "In a mouse model of ischemic stroke, platelets mediate HMGB1 release, resulting in detrimental NETs formation." (PMID 36892020, 2023). "By studying plasma, platelets, and thrombi from ischemic stroke patients, we identified platelet-derived HMGB1 as a potential mediator of platelet-induced NET formation during ischemic stroke." (PMID 35358095, 2022). "HMGB1, upon release after ischemic stroke, has been shown to bind several receptors, such as TLRs and RAGE, on immune cells to extend the initial damage caused by ischemic insult." (PMID 36232519, 2022). "In ischemic stroke with delayed t-PA treatment, the level of HMGB1 is significantly increased with 3-NT, which can be abolished by PDC." (PMID 35457061, 2022). "Elevated levels of HMGB1 were found in the serum of ischemic stroke patients and in the brain tissue of ischemic mice, and inhibition of HMGB1 improved ischemic brain injury in mice." (PMID 35967420, 2022). "Several studies have documented excessively raised levels of HMGB1 in both cerebrospinal fluid (CSF) and peripheral blood plasma/serum of ischemic stroke patients." (PMID 36232519, 2022). "After ischemic stroke, HMGB1 induces BBB degradation and increases the permeability of the BBB in the hyperacute phase." (PMID 36671605, 2022). "Together our results confirm a critical role for platelet-derived HMGB1 in the formation of detrimental NETs in the acute phase of ischemic stroke." (PMID 35358095, 2022). "This limits the clinical use of strategies targeting HMGB1 in ischemic stroke and emphasizes the importance of targeting detrimental downstream effects of HMGB1 signaling." (PMID 35358095, 2022). "High mobility group box 1 (HMGB1) is one such DAMP secreted by dying neurons following ischemic stroke." (PMID 35795678, 2022). "Here, we demonstrate that platelets substantially contribute to the rise in plasma HMGB1 levels in the acute phase of murine ischemic stroke." (PMID 35358095, 2022). "Consistent with a role for platelet-HMGB1-induced NET formation in ischemic stroke, thrombocytopenic mice were protected from brain injury (45.3 ± 20.3 mm3 vs. 88.2 ± 35.2 mm3) and had improved neurological function." (PMID 35358095, 2022). "We established that platelets induce detrimental NET formation during ischemic stroke through an HMGB1-dependent mechanism." (PMID 35358095, 2022).